ACE (angiotensin I converting enzyme)
Diseases named in the same sentence as ACE in open-access papers (continued):
Sharing a sentence is not in itself a finding about the gene and the disease.
glomerulosclerosis (15 papers, 2009 to 2025). A hardening of the kidney glomerulus caused by scarring of the blood vessels. "Like in earlier studies, we were unable to demonstrate beneficial effects of monotherapy with an AT1 antagonist or ACE inhibitor on glomerulosclerosis, nor of their combined treatment." (PMID 36106615, 2023). "For example, the protective effects of angiotensin-converting enzyme (ACE) inhibitors on glomerulosclerosis and albuminuria are blunted in aged animals." (PMID 33815880, 2021). "Intramedullary infusion of sodium butyrate in uninephrectomized rats resulted in the reversal of angiotensin-II-induced glomerulosclerosis and decreased the expression of the (pro)renin receptor, angiotensinogen, renin, angiotensin-I-converting enzyme and renal inflammatory markers." (PMID 36678139, 2023). "Other studies showed that aliskiren reduced albuminuria and glomerulosclerosis to a similar extent as the ACE inhibitor perindopril, despite lower BP reduction, and in non-diabetic mRen-2 rats, aliskiren and the ARB irbesartan similarly attenuated glomerular structural and functional changes." (PMID 20441574, 2010). "In addition to classical renin/ACE/Ang II/AT1 and AT2 axis, recent studies have shown that multiple new members of RAS system play critical role in both glomerularsclerosis and tubularsclerosis, with synergic or antagonistic effect to classical RAS." (PMID 25954204, 2015). "ACE inhibitors and AT1 antagonists lower blood pressure and improve albuminuria in this model, yet without preventing glomerulosclerosis." (PMID 36106615, 2023).
multiple myeloma (15 papers, 1980 to 2025). "Notably, one study assessed the ligand trap ActRIIA-Fc (ACE-011, Sotatercept) in patients with multiple myeloma and osteolytic lesions, demonstrating an improvement in bone mineral density." (PMID 41249489, 2025). "So, the real pathophysiological relationship between high serum ACE levels and AL amyloidosis is unknown." (PMID 24826302, 2013). "But we have not found any relationship with AL amyloidosis and serum ACE levels, and we do not know if this fact would have the same pathophysiological significance as in Aβ amyloidosis." (PMID 24826302, 2013). "Nevertheless, we have not found any description of elevated ACE levels in AL amyloidosis." (PMID 24826302, 2013). "Beta-2 microglobulin, parathyroid hormone (PTH), angiotensin-converting enzyme (ACE), and myeloma screen were negative." (PMID 40951148, 2025).
periodontitis (15 papers, 2015 to 2025). An acute or chronic inflammatory process that affects the tissues that surround and support the teeth. "The adjusted odds ratios for the effects of medications between the periodontitis and healthy groups revealed that anticoagulants, statins and ACE inhibitors are significantly (p < 0.05) associated with periodontitis." (PMID 37888091, 2023). "All six medication types including bisphosphonates, proton pump inhibitors, antidepressants, anticoagulants, statins and ACE inhibitors were significantly associated with periodontitis." (PMID 37888091, 2023). "In the Caucasian population with chronic periodontitis, the occurrence of alleles characterized by deletion (absence of a DNA fragment) and insertion (presence of an additional DNA sequence) in the ACE coding gene was assessed." (PMID 35454140, 2022). "Other enzymes whose gene polymorphisms were studied for association with periodontitis include the angiotensin-converting enzyme (ACE) and N-acetyltransferase (NAT2)." (PMID 35454140, 2022). "Certain medications—such as anti-coagulants, statins, and ACE inhibitors—have been linked to a higher risk of periodontitis, which may in turn exacerbate furcation defects." (PMID 41302318, 2025). "Angiotensin-converting enzyme (ACE) inhibitors may modulate local immune responses and vascularity, but Mendelian randomization and observational data suggest that ACE inhibitors are associated with an increased risk of acute periodontitis." (PMID 41302318, 2025). "Recently, another study evaluating individuals from the greater Stockholm area, Sweden, reported a possible relationship between taking systemic medications, such as anticoagulants, ACE inhibitors, statins, and periodontitis stages III and IV." (PMID 39157205, 2024). "Patients who reported taking anticoagulants, statins and ACE inhibitors demonstrated 3.546 (95% CI: 1.982, 6.343), 2.771 (95% CI: 1.877, 4.09) and 4.847 (95% CI: 2.785, 8.434) times higher odds of having periodontitis, respectively." (PMID 37888091, 2023). "Patients who reported taking anticoagulants, statins and ACE inhibitors demonstrated 3.546 (95% CI: 1.982, 6.343), 2.771 (95% CI: 1.877, 4.090) and 4.847 (95% CI: 2.785, 8.434) times higher odds of having periodontitis, respectively (p < 0.001)." (PMID 37888091, 2023). "ANRI and ANRII expressions and angiotensin-converting enzyme (ACE) activity are increased in the tissues of periodontitis patients." (PMID 34684229, 2021). "However, when subjects were sub-grouped based on BMI and compared, there was a significant difference in Chao1 and ACE diversity indices in the obese group (p < 0.05), as subjects with MS periodontitis had lower indices than those with NM periodontitis." (PMID 36839184, 2023). "Hypoglycemic agents, calcium channel blockers, insulin and diuretics were significantly higher in the periodontitis patients, while a higher intake frequency of angiotensin-converting enzyme (ACE) inhibitors and antidepressants was also found in the periodontitis group." (PMID 37888091, 2023). "Meanwhile, assessing the incidence of the composite genotype, simultaneously including genes for both ACE and TNF-β, it was found that in patients with chronic periodontitis, the DD genotype for ACE and—at the same time—the B2B1 genotype for TNF-β occurred much more frequently." (PMID 35454140, 2022). "Notably, numerous people are treated with ACE inhibitors to combat cardiovascular and renal diseases which can exist simultaneously with periodontitis." (PMID 26244896, 2015). "A significant increase in the gene expression of ACE, AT1 receptors and inflammatory mediators, such as proinflammatory cytokines, has been reported in ligature-induced periodontitis." (PMID 34884653, 2021). "In contrast, the presence of periodontitis did not increase ACE activity." (PMID 26244896, 2015).
periodontitis (continued). "However, gingivae from volunteers with periodontitis had moderate ACE activity and were not significantly different from either healthy or gingiva homogenates (p-value > 0.05)." (PMID 26244896, 2015). "Gingiva homogenates from the healthy, gingivitis and periodontitis groups all generated Ang II, Ang 1–9 and Ang 1–7 when incubated with a precursor (Ang I or Ang II) as determined by HPLC, indicating that ACE, ACE-2, and other enzymes that form Ang II were present and functional." (PMID 26244896, 2015). "Thus the conversion of Ang I to Ang II induced by ACE could be more important in the initiation and progression of healthy tissue to gingivitis and/or gingivitis to periodontitis rather than the maintenance of chronic periodontitis." (PMID 26244896, 2015).
aneurysm (14 papers, 2009 to 2025). Bulging or ballooning in an area of an artery secondary to arterial wall weakening. "The walls of aneurysms show less presence of the angiotensin converting enzyme (ACE) and angiotensin II receptor type 1 (AT1), which causes a thinning of the arterial wall and a lack of vascular remodeling." (PMID 36499752, 2022). "For AAAs, metformin, ACE inhibitors, angiotensin II receptor antagonists, and thiazides are linked to slower growth, emphasizing the importance of cardiovascular risk management and the potential of metformin in reducing aneurysm growth." (PMID 39728269, 2024). "In particular, both ACE, which is a positive modulator of Angiotensin II signaling, and Thbs1, a multifunctional protein with both pro-inflammatory and cell signaling regulatory functions, have been shown to be upregulated in aneurysm tissue and implicated in its pathogenesis." (PMID 35463747, 2022). "A sub-analysis on patients who were on ACE inhibition for the total study period and those not on an ACE inhibitor revealed similar AAA progression in the two groups, thus challenging a major effect of ACE inhibition on aneurysm progression." (PMID 25474105, 2014). "The clinical management of AA using beta-blockers, calcium channel blockers, and angiotensin-converting enzyme (ACE) inhibitors limit AA progression but do not lead to reductions in aneurysm growth or the risk of rupture." (PMID 35453919, 2022). "Contrary to patients without ACE inhibition, aneurysm patients showed lower Ang 1–7 levels as controls, with a shift to an increased level of Ang 1–5 (5.9 vs. 1.8, p-value = 0.061)." (PMID 40003968, 2025). "Additionally, aneurysm patients under ACEi had lower ACE2 activity (p-value = 0.042) and slightly higher ACE activity (p-value = 0.067)." (PMID 40003968, 2025). "A possible effect of ACE-inhibitors on AAA growth was evaluated in a sub analysis of data from the PHAST trial, a study aimed at evaluating the effect of doxycycline treatment in patients under surveillance for a small aneurysm." (PMID 25474105, 2014). "Because of the overrepresentation of patients with diabetic disease in the ACE-inhibitor group, and the apparently reduced AAA progression in patients with diabetic disease on aneurysm progression we repeated the analysis after exclusion of patients with diabetic disease." (PMID 25474105, 2014). "Evaluation of data from the PHAST cohort did not indicate an effect of ACE inhibitors on 18-month aneurysm progression (mean difference at 18 months: −0.24 mm (95% CI: −0.90–0.45, P = NS)." (PMID 25474105, 2014). "In addition, the angiotensin-converting enzyme (ACE) inhibitor enalapril, which blocks AngII formation, did not adequately inhibit aneurysm formation, regardless of the same antihypertensive effect as losartan." (PMID 30037098, 2018). "This evaluation did not indicate an effect of ACE inhibitors on aneurysm growth." (PMID 25474105, 2014). "This trail was not designed to test an effect of ACE inhibitors on aneurysm growth." (PMID 25474105, 2014).
dyslipidaemia (14 papers, 2008 to 2024). "On the other hand, other studies noted that the association between the ACE I/D polymorphism and dyslipidaemia was insignificant in Chinese diabetic patients." (PMID 39080710, 2024). "Odds ratio analysis of FTO rs9939609, MC4R rs17782313, ACE I/D rs4646994 and MTHFR C677T rs1801133 polymorphisms with somatometric and dyslipidaemia variables among the Liangmai and Mizo tribes of Manipur." (PMID 34414818, 2021). "Genetic interaction results between FTO rs9939609, MC4R rs17782313, ACE I/D rs4646994 and MTHFR C677T rs1801133 for somatometric and dyslipidaemia variables using generalized multifactor dimensionality reduction (GMDR)." (PMID 34414818, 2021).
gastric cancer (14 papers, 2008 to 2025). A primary or metastatic malignant neoplasm involving the stomach. "While ATGIIR1 overexpression has been associated with invasion and angiogenesis in ovarian cancer, the insertion/deletion polymorphism (ACE I/D) of ACE, especially the DD-genotype, is involved in early gastric cancer development and increased lymph node metastasis." (PMID 39350850, 2024). "Further suggestions obtained from the finding of lower cancer risk exhibited by individuals homozygous for I or A alleles at the ACE gene, which is associated with lower ACE levels, as well as lower risk of tumor progression in patients with gastric cancer carrying the polymorphism." (PMID 18947424, 2008). "The expression of Ang II, AT1, and the ACE activity in gastric cancer patients is upregulated in comparison to healthy tissues." (PMID 37891636, 2023). "The most studied RAAS axis in gastric cancer is the ACE/Ang II/AT1R which is found to elaborate on many mechanisms involved in cancer progression." (PMID 37891636, 2023). "Furthermore, ACE was expressed by endothelial cells in 100% collected specimens of gastric cancer at immunohistochemistry." (PMID 34399734, 2021). "The aim of our study was to evaluate potential associations between the presence of gastric cancer (GC) and high risk atrophic gastritis (HRAG) and polymorphisms of genes encoding Angiotensin converting enzyme (ACE), Nod-like receptor 1 (NOD1), Toll-like receptor 4 (TLR4) and FAS/FASL." (PMID 21864388, 2011). "In another study on gastric cancer patients, it is demonstrated that the AT2 expression along with AT1 and ACE was increased compared to healthy tissues." (PMID 37891636, 2023).
glaucoma (14 papers, 2015 to 2025). Increased pressure in the eyeball due to obstruction of the outflow of aqueous humor. "Angiotensin-converting enzyme (ACE) inhibitors have recently received attention as a new class of drug possessing the ability to lower IOP to treat glaucoma." (PMID 35745720, 2022). "In recent years, there has been a renewed interest in the role of Ang II in mediating the pathogenesis of glaucoma and angiotensin-converting enzyme (ACE) inhibitors have emerged as a new class of drugs for the treatment of glaucoma." (PMID 32513477, 2020). "Oculohypotensive effects of ACE inhibitor Perindopril have also been reported in both acute and chronic experimental models of glaucoma, as recently also the anti-glaucomatous effects of the activation of intrinsic angiotensin-converting enzyme 2 in an experimental glaucoma." (PMID 25677099, 2015). "Angiotensin converting enzyme Alu-repeat deletion/insertion (ACE I/D) emerged as a candidate gene polymorphism, which may play a role in the alteration of the circadian IOP variability in advanced glaucoma." (PMID 33396443, 2020). "Some studies have shown that ACE inhibitor reduces the IOP and have a protective effect against glaucoma, but it has also been shown that the peptide angiotensin II is a modulator or transmitter in retinal neurophysiology." (PMID 27872861, 2016). "For instance, the effects of blockers of the ACE/Ang II/AT1 receptor axis on IOP have been evaluated in animals and patients with glaucoma." (PMID 26204514, 2015). "In patients with primary open-angle glaucoma (POAG), levels of angiotensin-converting enzyme (ACE) in tears are elevated compared to non-glaucomatous controls." (PMID 41226756, 2025). "The level of ACE in the aqueous humour of patients with glaucoma is significantly greater than that in nonglaucoma patients; furthermore, the expression of ACE in the aqueous humour of patients without glaucoma is lower than that of ACE2, which controls intraocular pressure by interacting with ACE." (PMID 39967658, 2025).
gout (14 papers, 2012 to 2024). A condition characterized by painful swelling of the joints, which is caused by deposition of urate crystals. "It has been previously demonstrated that ACE inhibitors increase the probability of acute gout inflammation induced by monosodium urate, which was reported to enhance B1R signaling." (PMID 26244896, 2015). "This is due to the fact that ACE inhibitors activate B1 receptors by blocking the breakdown of bradykinin; however, ACE inhibitors appear to work in the opposite direction in animal models of gout attacks, worsening pain." (PMID 37237567, 2023). "The results showed that species richness based on the ACE and Chao1 indices was significantly decreased in mice with gout, while the microbial diversity as assessed by Shannon and Simpson indices showed a significant decrease in mice with gout." (PMID 35145506, 2022). "In contrast to the joint-protective effects reported in OA model, ACE inhibitors contribute to the onset of gout attacks in a facilitatory manner by lowering the threshold of monosodium urate crystals mass required for the onset of acute gout attacks in a bradykinin B1 receptor-dependent manner." (PMID 37237567, 2023).
pancreatic cancer (14 papers, 2010 to 2025). "Our results demonstrate a significant positive impact of ARBs, ACE inhibitors, and CCBs on survival in patients with pancreatic cancer treated with gemcitabine." (PMID 39340700, 2024). "Our results are compatible with the previously reported association between the ABO gene and pancreatic cancer, and show that the effect of these common variants at the ABO locus on the P-LIP and ACE levels is largely opposing and pleiotropic." (PMID 24586218, 2014). "We retrospectively investigated the impact of angiotensin I-converting enzyme inhibitors (ACEIs) and angiotensin II type-1 receptor blockers (ARBs) in 155 patients with pancreatic cancer receiving gemcitabine monotherapy." (PMID 20978506, 2010). "More prospective clinical evidence is required to fully determine the benefits of ARBs, ACE inhibitors, CCBs, and metformin on survival in patients with pancreatic cancer before treatment recommendations can be made regarding their use, duration, and dosage in the broader target population." (PMID 39340700, 2024). "Various ACE inhibitors have been shown to suppress tumor growth and/or blood vessel formation in mouse models of squamous cell cancer, hepatocellular carcinoma, pancreatic cancer and renal cell carcinoma." (PMID 37749499, 2023). "In mice bearing NTS1R-expressing pancreatic cancer xenografts, [99mTc]Tc-DT9 showed significantly higher tumor uptake compared with the [99mTc]Tc-DT1 reference, while during twin ACE/NEP inhibition, uptake was comparable between these analogs." (PMID 37631306, 2023). "In the present study, we were interested in exploring the efficacy of [99mTc]Tc–DT1 to target NTS1R–positive pancreatic cancer during NEP and ACE inhibition in mice models." (PMID 33114537, 2020). "Aiming toward translation of this promising approach in NTS1R-positive pancreatic ductal adenocarcinoma (PDAC) patients, we now report on the impact of registered NEP/ACE inhibitors on the performance of [99mTc]Tc–DT1 and [99mTc]Tc–DT5 in pancreatic cancer models." (PMID 33114537, 2020). "Some tumor markers (CA19-9, ACE y AFP) were negative, but ultrasound exams and tomography revealed a tumor that was strongly suggestive of pancreatic cancer." (PMID 28789670, 2017).
vasculitis (14 papers, 2014 to 2025). "These pathological processes reduce ACE activity and cause an AngII/Ang1-7 imbalance, leading to vasculitis and thrombosis." (PMID 40084335, 2025). "One patient with IgA nephritis received an angiotensin-converting enzyme (ACE) inhibitor, one patient with interstitial nephritis was treated with corticosteroids, and one patient with vasculitis received corticosteroids and rituximab." (PMID 33900582, 2021). "Due to atypical presentation, further investigations for differential diagnosis, a vasculitis screen, myelin oligodendrocyte glycoprotein (MOG) antibodies and serum angiotensin-converting enzyme (ACE) level investigations were done." (PMID 39703256, 2024).